CD4 (CD4 molecule)
Diseases named in the same sentence as CD4 in open-access papers (continued):
Sharing a sentence is not in itself a finding about the gene and the disease.
HIV-1 infection (continued). "Additionally, Vpr accelerates acute HIV-1 infection by exploiting proliferating CD4+ T cells, including regulatory CD4+ T cells, through G2 arrest and apoptosis in vivo." (PMID 34835114, 2021). "Finally, Vpu induces virion release by preventing the action of host restriction factors, downregulating CD4 during the late stages of HIV-1 infection, and impeding Nuclear factor-kappa-light-chain-enhancer of activated B cells (NF-κB) activation." (PMID 32841065, 2021). "Latently infected resting CD4+ T cells constitute a major reservoir of persistent HIV-1 infection." (PMID 33688006, 2021). "Finally, we analyzed the relationship between immune activation and platelet-CD4+ T cell aggregate formation during HIV-1 infection." (PMID 34987521, 2021). "However, it is apparent that IFN-I-mediated activation induces the apoptosis of CD4+ T cells during HIV-1 infection." (PMID 33924786, 2021). "When compared to CD4-depleted exosomes derived from CD4+ T cells, CD4+ exosomes inhibit HIV-1 infection, which may be due to the disguising of HIV-1 envelope proteins by exosomal CD4, resulting in the inhibition of HIV infection." (PMID 33567490, 2021). "We next focused on characterizing whether GPI-m36.4 is capable of protecting human CD4+ T cells from HIV-1 infection." (PMID 33462383, 2021). "In addition they observed that levels of both pyroptosis and apoptosis in CD4 + T cells were significantly elevated during HIV-1 infection, and were decreased following antiretroviral therapy." (PMID 33883686, 2021). "Either the extended time in culture or the HIV-1 infection conditions in the CCL19 model may sensitize primary CD4+ T cells to cytotoxic effects of celastrol." (PMID 33914760, 2021). "In addition to increased CD8+ T cell activation we report heightened activation of CSF CD4+ T cells and monocytes during acute HIV-1 infection." (PMID 34874976, 2021). "This suggests that clonal expansion of latently HIV-1–infected CD4+ T cells might already start during primary HIV-1 infection." (PMID 33784259, 2021). "However, the phenotypic characteristics and clinical significance of platelet-CD4+ T cell aggregates are yet to be determined in HIV-1 infection." (PMID 34987521, 2021). "However, evidence of CSF inflammation and viral detection within two weeks of HIV-1 infection along with very early compartmentalization of HIV-1 sequences in the CNS indicate an early phase of viral entry when CD4+ T cells are more likely to be involved." (PMID 34874976, 2021). "Likewise, Mycobacterium Hsp70 has been shown to interact with CCR5, abrogating HIV-1 infection of human CD4+ T cells." (PMID 35145925, 2021). "Also, ZFNs targeting the CXCR4 co-receptor on CD4+ T cells have shown success in protecting from HIV-1 infection in humanized mice, although resistance was eventually lost upon selection for CCR5-tropic mutants." (PMID 33868262, 2021). "In HIV-1 infection, however, it seems that the high rates of CD4+ T-cell death are the consequence rather than the cause of immune activation." (PMID 33924786, 2021). "Activated CD4+ T cells are the main cell type that support HIV-1 infection." (PMID 35126374, 2021). "Our data suggest that personalized epigenetic and functional changes to monocyte cells during acute HIV-1 infection may be an important factor in CD4 T cell recovery in the setting of HIV-1." (PMID 34388205, 2021). "CD155 expression on CD4 T cells was inversely with CD4 T-cell counts in acute HIV-1 infection (r = −0.53, P = 0.0017) including the first, third month of infection, and in chronic HIV-1 infection (r = −0.54, P = 0.0004) including the twelfth month, over 2 years of infection." (PMID 33717085, 2021). "Besides, Nef promotes HIV-1 infection through the sequestration of CD4 and MHC class 1 molecules into MVBs to degradation, because the presence of CD4 molecules on the exosomal surface can inhibit viral transmission through adhesion to the viral envelope." (PMID 34055668, 2021).
HIV-1 infection (continued). "Notably, prophylactic treatment with carbamazepine or everolimus decreased HIV-1 infection of both CD11c+ DCs and CD4+ T cells." (PMID 33637808, 2021). "HIV-1 infection is known to induce downregulation of CD4 surface expression." (PMID 33688006, 2021). "Indeed, genital tract inflammation during early HIV-1 infection predicts an increased risk for HIV acquisition, and higher viral load at set point and CD4+ T cell depletion in women." (PMID 34512664, 2021). "Therefore, the lack of LAPTM5 is likely to be the reason why Vpr is dispensable for HIV-1 infection of primary CD4+ T cells." (PMID 34140527, 2021). "In addition, CD4+ memory T cells, that are usually infected by primary HIV-1 infection, act as major latent HIV reservoirs during inflammatory events, even when ART is used." (PMID 32841065, 2021). "Initially, we sought to test the compounds’ antiviral activity in Jurkat cells, which does not require stimulation and whose susceptibility to HIV-1 infection is less variable than that of primary CD4+ T cells." (PMID 34819367, 2021). "Reduced iNKT cell CD4+ subsets as a result of HIV-1 infection may skew iNKT cell functionality toward cytotoxicity." (PMID 31190065, 2020). "In summary, EBV transformation can induce B-cell susceptibility to HIV-1 infection in vitro in a CD4- and CXCR4-dependent manner, similar to IL-4 and/or CD40L stimulation of B cells and CD4 can be detected on peripheral blood B cells and lymphoma cells in EBV-associated diseases." (PMID 32576602, 2020). "Robust and sustained CD4 T cell proliferative responses to the Gag p24 antigen correlated with control of viremia and lack of disease progression after long-term transfusion-acquired HIV-1 infection." (PMID 32462053, 2020). "We undertake a case-control study, CD4+ cell count used as a surrogate marker for HIV-1 infection." (PMID 32565728, 2020). "Importantly, Cul3 was detected in activated CD4+ T cells, the primary target of the virus, which further supports a role of this factor in regulating HIV-1 infection." (PMID 32882949, 2020). "Our data suggest that the protective effect of the MAVS minor genotype is associated with control of HIV-1 infection in CD4+ T cells in the PBMC culture, rather than by an intrinsic restriction in CD4+ T cells." (PMID 32708557, 2020). "We did observe differential HIV-1 gene expression upon HIV-1 infection in LCLs compared with autologous HIV-1–infected CD4+ T cells, which may be explained by different HIV-1 replication dynamics in LCLs compared with T cells." (PMID 32576602, 2020). "In summary, these results demonstrate for the first time that the triple HIV-1 infection might reduce CD4+ T-cell counts, which would predict a more rapid disease progression." (PMID 32038599, 2020). "While two previous studies found IFN-λ1 or IFN-λ2 could inhibit or enhance HIV-1 infection of CD4+ T cells, our findings support the IFN-λ3-mediated induction of an antiviral program in CD4+ T cells, with no indication of an enhancement of infection." (PMID 32353085, 2020). "Alterations in IFNAR expression in mucosal CD4+ T cells during HIV-1 infection may also contribute to our results, but our recent study have not detected significant changes in IFNAR2 expression in mucosal immune cells in PWH." (PMID 33064743, 2020). "Here, we elucidate the dynamics of CD161+ CD4+ T cells in HIV-1 infection." (PMID 33322496, 2020). "Overall, these studies highlight a gap in our understanding of HIV-1 reservoirs, demonstrating the need to better understand the integration site landscape in the context of tissue/blood compartments and CD4+ T cell heterogeneity at different stages of HIV-1 infection." (PMID 32970634, 2020). "Most ISGs are upregulated in the chronic phase of HIV-1 infection in viremic untreated patients and their expression is positively correlated with the percentage of activated T cells and negatively correlated with CD4+ T cell counts." (PMID 32615986, 2020).
HIV-1 infection (continued). "In particular, the engraftment of human CD34+ fetal liver or umbilical cord-derived blood stem cells into highly immunodeficient NSG (NOD/Ltsz-scid/scidγcnull) mice allows reconstitution of a leukocyte pool that is human-derived, allowing chronic HIV-1 infection of the human CD4+ T cells." (PMID 32582133, 2020). "During the initial stages of HIV-1 infection, when Langerhans cells may be infected and virus amplification in CD4+ T cells is critical, TGF-β1 may thus have a beneficial role overall." (PMID 33329587, 2020). "Because HIV-1 infection also sensitizes CD4 T cells to extrinsic apoptosis induced by FAS ligation, we also questioned whether bryostatin-1 would inhibit FAS-mediated apoptosis in HIV-infected cells." (PMID 33075109, 2020). "Indeed, IFI16 silencing or pharmacological inhibition of reverse transcription in resting human CD4 T cells prevents caspase-1 activation and cell death following abortive HIV-1 infection." (PMID 31786265, 2020). "Chronic HIV-1 infection is associated with loss of the CD161+ CD4 T cell population, and non-human primate studies suggest that their depletion is associated with disease progression." (PMID 33322496, 2020). "Although HIV-1 protein expression could still be detected in some T cells before the start of ART, these data suggest that latent HIV-1 infection has been established in human CD4+ T cells in these Hu-HSC mice." (PMID 32792548, 2020). "Overall, our findings indicate that the innate and Th17-like CD161+ CD4+ T cells are severely affected during acute stages of HIV-1 infection, and that early ART initiation may preserve these cells in the colon." (PMID 33322496, 2020). "The decline in CD4+ MAIT cells observed here is different from the preservation of CD4+ MAIT cells seen in previous studies of chronic HIV-1 infection, and may indicate that this small subpopulation is susceptible to infection." (PMID 31937782, 2020). "Antibodies (Abs) specific for CD4-induced envelope (Env) epitopes within constant region 1 and 2 (C1/C2) were induced in the RV144 vaccine trial, where antibody-dependent cellular cytotoxicity (ADCC) correlated with reduced risk of HIV-1 infection." (PMID 32605979, 2020). "Acute HIV-1 infection results in immune activation that may drive the formation of a more differentiated CD4+ T cell pool and thus more cells expressing CCR5." (PMID 32762760, 2020). "Similarly, infection of Daudi-CD4+ cells, permissive to HIV-1 infection, with wt HIV-1 or VSV-G pseudotyped wt HIV-1 generated UNG2 depletion reaching 48% and 92%, respectively." (PMID 32778120, 2020). "Since the CCR5 gene of primary CD4+T cells could be edited by Adv-AsCpf1-#4/#5, like TZM.bl and SupT1-R5 cell line, we next examined whether the edited primary CD4+ T cells could defense HIV-1 infection." (PMID 32670545, 2020). "Similarly, monocytes express CD4, albeit at very low levels, yet are largely resistant to HIV-1 infection in vitro and infected monocytes are rarely found in the blood of HIV-infected people on or off ART." (PMID 32992787, 2020). "We also addressed whether ART initiated during the chronic or acute phase of HIV-1 infection was associated to the markers present on CD8 + and CD4 + T cells in the CyTOF panel utilized in this work." (PMID 33235273, 2020). "While there are no known variants of CD4 in humans that affect the efficiency of HIV-1 infection, CD4 is highly variable in chimpanzees, and this variation is responsible for restricted susceptibility to SIV, the progenitor of HIV-1." (PMID 33322320, 2020). "However, to what extent innate sensing occurs in CD4+ T cells during HIV-1 infection is still under debate." (PMID 31968566, 2020). "We used HIV-1 infection of purified CD4+ T cell cultures to monitor whether pre-incubation of IFN-λ3 before HIV-1 inoculation leads to decreased viral infection in the absence of any other immune cells." (PMID 32353085, 2020).
HIV-1 infection (continued). "In addition, the present study demonstrated that tear viral load was associated with blood viral load, CD4+ T cell count, CD4+/CD8+ T cell count, duration of HIV-1 infection." (PMID 32845429, 2020). "With activation these cells may exhibit clonal expansion releasing HIV-1 of limited genotypes or they may initiate a broader local HIV-1 infection with other activated CD4+ T-cells providing targets for further local amplification." (PMID 32697807, 2020). "Reseaches advancedly disclosed upregulated Glut1 expression as the underlying mechanism and verified the association by that siRNA-mediated Glut1 down-regulation could abrogate HIV-1 infection of quiescent CD4+ T cells." (PMID 33117366, 2020). "On the other hand, the IFN response may become detrimental in the chronic phase of HIV-1 infection and has been related to poor antiviral response, higher virus loads and lower CD4 counts." (PMID 32760119, 2020). "The cytokine profile of CMV-specific CD4+ T cells provide survival benefit during HIV-1-infection." (PMID 31910871, 2020). "Inhibition of glycolysis impaired HIV-1 infection in cell culture in all CD4+ T cell types." (PMID 32084246, 2020). "Also, the CD4+ TCM subset has been well-established to be the preferential circulating reservoir in chronic HIV-1 infection." (PMID 32194543, 2020). "Metabolically highly active CD4+ T cells seems more prone to HIV-1 infection." (PMID 33117366, 2020). "We have previously shown that Vpr expression in the context of HIV-1 infection markedly decreases UNG2 expression in transformed or primary CD4 + T lymphocytes, and demonstrated for the first time that Vpr-UNG2 interaction significantly impairs the uracil excision activity of these infected cells." (PMID 32778120, 2020). "In this study, we investigated whether targeting S1P could inhibit the establishment of HIV-1 infection and the generation of the latent reservoir in CD4 T cells." (PMID 32790802, 2020). "However, there was no statistical difference regarding sex/gender, current age, age at infection, years of HIV-1 infection, years on ARTc, nadir, CD4/CD8 ratio or logVL between both groups." (PMID 32187205, 2020). "In addition, Hif-1α can also be activated in non-hypoxic conditions, such as during human immunodeficiency virus (HIV)-1 infection in CD4 T cells, in which CD4 T cells are largely depleted via cell apoptosis." (PMID 33644036, 2020). "Once within the mucosal tissues, activated CD4+ T cells are the primary target for HIV-1 infection." (PMID 32582133, 2020). "We further decided to determine whether enhanced HIV-1 infection in CD4+ T cells required cell-cell interactions." (PMID 31772057, 2019). "As we demonstrated the efficient disruption of CCR5 by SaCas9/sgRNA in vitro, we wanted to evaluate whether CRISPR/SaCas9-mediated disruption of CCR5 could protect primary CD4+ T cells against HIV-1 infection in vivo." (PMID 31186067, 2019). "Moreover, AIDS seem to occur at a relatively lower viral load level in HIV-2 compared with HIV-1 infection, although the CD4 count is often higher in HIV-2-infected subjects when AIDS-defining illnesses develop." (PMID 31484562, 2019). "To test the hypothesis that HIV-1 infection can induce miRNA expression in CD4 T cells, which may be transferred to endothelial cells by EVs, we first developed an ex vivo model to obtain CD4 T cell-derived EVs from HIV-1-infected patients." (PMID 31311940, 2019). "The rise of the CD4/CD8 ratio was previously linked with reduced levels of HIV DNA in peripheral blood cells, mainly if cART was established during primary HIV-1 infection." (PMID 30804915, 2019). "Spermatozoa enhances HIV-1 infection, especially of DCs, but also of macrophages and CD4+ T cells." (PMID 30702421, 2019). "In this study, we hypothesized that HIV-1 infection induces cellular miRNA expression in CD4 T cells, which may be carried by EVs and transferred in a paracrine manner to endothelial cells to regulate vascular homeostasis." (PMID 31311940, 2019).
HIV-1 infection (continued). "However, it has been demonstrated that the HDAC inhibitor vorinostat (SAHA) promoted HIV-1 infection in CD4 + T cells, by enhancing the efficiency of post-entry events, including reverse transcription, nuclear import, and integration." (PMID 31744547, 2019). "Since we observed an expansion of CECs in the peripheral blood of HIV-infected individuals —in particular, a positive correlation between the frequency of CECs with the plasma viral load —we decided to investigate how CECs influence HIV-1 infection in CD4+ T cells using an ex vivo infection assay." (PMID 31772057, 2019). "Resting CD4+ T cells are major reservoirs of latent HIV-1 infection, and may be formed during the early phase of the infection." (PMID 31036079, 2019). "However, it has also been suggested that resting CD4+ TN cells are an important reservoir of latent HIV-1 infection." (PMID 31036079, 2019). "However, only 1 in 106 of these latently-infected resting memory CD4+ T-cells are capable of reactivating productive HIV-1 infection upon stimulation." (PMID 31487807, 2019). "Furthermore, HIV-1 infection promotes a generalized activation of host responses that involve CD4 T cells and cells of the microenvironment, such as endothelial cells, which are not directly infected." (PMID 31311940, 2019). "At this point, HIV-1 infection resulted in a trend toward suppression of Toll-like receptor 3 (TLR3) protein expression on splenic but not peripheral CD4 T cells, whereas peripheral TLR7 and TLR9 protein expression was elevated after HIV-1 infection of both CD4 T cells and macrophages." (PMID 30867315, 2019). "Further, semen has been shown to inhibit HIV-1 infection of CD4+ T cells." (PMID 30702421, 2019). "Moreover, we showed survival and enrichment of CCR5-disrupted CD4+ T cells in humanized mice during R5-tropic HIV-1 infection." (PMID 31186067, 2019). "To investigate whether Lactobacillus-derived EVs affect HIV-1 infection, we infected two human CD4+ T cell lines, MT-4 and Jurkat-tat, with this virus." (PMID 31827089, 2019). "This internalization efficiency may contribute to SE interference with HIV-1 infection of epithelial cells within the female reproductive tract by reducing HIV-1 transcytosis across the mucosa to reach CD4+ target cells." (PMID 30702421, 2019). "To evaluate whether the modification of CCR5 in primary human CD4+ T cells by CRISPR/SaCas9 could render the cells resistant to HIV-1 infection, we infected the CD4+ T cells with HIV-1YU2 and then cultured these cells for 7 days." (PMID 31186067, 2019). "Primary CD4+ T cells were isolated from three healthy individuals and subjected to HIV-1 infection." (PMID 31888084, 2019). "To further confirm whether the CD161+ CD4+ T cells among the Th17 and Th1Th17 cell subsets were highly permissive to HIV-1 infection, we performed an in vitro infectivity assay." (PMID 31594817, 2019). "Although, these terminally differentiated latently infected macrophages cannot proliferate, they could be able to spread HIV-1 infection to CD4+ T cells upon reactivation of the virus by LRAs." (PMID 31866988, 2019). "In addition, NK cell killing of CD4 T cells has also been postulated to participate in the decline of CD4 T cells in HIV-1 infection." (PMID 30814283, 2019). "HIV-1 infection is dependent on the binding of Env to CD4 and coreceptors on target cells." (PMID 31269971, 2019). "Moreover, a second mechanism related with CDKN1A has been associated with EC phenotype, describing a partial resistance of CD4+ T cells from these individuals to HIV-1 infection mediated by a strong and selective upregulation of CDKN1A, also called p2124." (PMID 31582776, 2019). "This indicates that HIV-1 infection may place selective pressure on CCR5-modified CD4+ T cell survival." (PMID 31186067, 2019). "However, among these, we identified 16 highly upregulated genes in CD4+ T cells when cocultured with CECs, which can be associated with CEC-mediated enhanced HIV-1 infection." (PMID 31772057, 2019).